C12orf54 (chromosome 12 open reading frame 54)
Synonyms: HSD-29; HSD-30; MGC35033
Tractability: No criterion of Open Targets' tractability assessment is met for any kind of drug.
Gene: Protein-coding gene on chromosome 12 (48,482,498 to 48,496,524, forward strand). Ensembl gene ENSG00000177627.
Subcellular location (Human Protein Atlas): Intermediate filaments; Cytosol
Gene Ontology:
Cellular component: cytosol; intermediate filament cytoskeleton
Genetic constraint (gnomAD): Loss-of-function variants: 21 observed, 24.71 expected, observed/expected ratio (o/e) 0.85, 90% interval 0.6 to 1.22. The upper end of that interval is the gene's LOEUF score, 1.22, which puts it in group 5 of 6, group 1 being the genes least tolerant of losing a copy. Missense variants: 140 observed, 144.23 expected, observed/expected ratio (o/e) 0.97, 90% interval 0.85 to 1.12. Synonymous variants: 49 observed, 46.22 expected, observed/expected ratio (o/e) 1.06, 90% interval 0.84 to 1.35.
Homologues: Orthologues: macaque C11H12orf54 (72% identical), pig C12orf54 (59% identical), dog C12orf54 (54% identical).
Diseases named in the same sentence as C12orf54 in open-access papers:
C12orf54 is named in the same sentence as 3 diseases in open-access papers, as found by Europe PMC text mining. Sharing a sentence is not in itself a finding about the gene and the disease. The quoted sentences say what the papers report.
Sleep apnea (1 paper, 2023). An intermittent cessation of airflow at the mouth and nose during sleep is known as sleep apnea. "The results showed that Lasso regression identified a total of seven genes as the characteristic genes of sleep apnea, which are: C12orf54, FOS, GPR1, OR9A4, MYO5B, RAB39B, KLHL4, as the core genes of follow-up research and construction of prediction models." (PMID 38077447, 2023).
C12orf54 also shares sentences with these, for which no sentence is quoted: cardiovascular disease (1 paper); endothelial dysfunction (1).